TBK1 (TANK binding kinase 1)
Diseases named in the same sentence as TBK1 in open-access papers (continued):
Sharing a sentence is not in itself a finding about the gene and the disease.
tumor (continued). "And abnormalities also involve gene mutations in PTEN, SIRPA, TBK1, the Y chromosome, as well as immune cells and stromal cells such as Treg, MDSCs, TAMs, CAFs, loss of tumor immunogenicity, abnormalities in Indoleamine 2,3-dioxygenase, Ubiquitin-specific protease 12 (USP12), and Hypoxia." (PMID 39567970, 2024). "Strikingly, in both STING-deficient and IRF3-deficient mice, there was a substantially diminished CD8+ T cell response against tumor-associated antigens and, in wild-type mice, transfer of tumor DNA to host APCs resulted in TBK1 and IRF3 phosphorylation and, as a consequence, production of IFN-β." (PMID 29050360, 2017). "The exact mechanisms underlying the silencing of STING and TBK1 in tumor patients remain unclear." (PMID 40083918, 2025). "When comparing strategies for manipulating RIPK1, direct activation of RIPK1 through the loss of checkpoint kinases such as TBK1/IKKε may exhibit higher efficiency in tumor killing than knockout strategies, such as RIPK1 KO or PROTAC-mediated degradation, which eliminate the protein entirely." (PMID 41315176, 2025). "Our accumulated evidence suggests that the loss of TBK1 and IKKε may sensitize tumor cells to T cell killing and is associated with reduced pro-survival RIPK1 S25 phosphorylation within the TNFR1 complex, thereby promoting RIPK1 activation and subsequent cell death." (PMID 41315176, 2025). "This corresponded with the strongest activation of the cGAS-STING pathway in tumor lysates, as evidenced by maximal expression of p-TBK1, p-IRF3, and IFN-β." (PMID 41356181, 2026). "Conversely, TBK1 inhibition has recently been shown to improve responses to PD-L1 blockade in cancer immunotherapy by lowering the cell death threshold of tumor cells." (PMID 40053580, 2025). "The ubiquitin-proteasome system or autophagy, which contributes to the degradation of STING and TBK1, has been shown to favor the growth of different tumor types 6-9." (PMID 40083918, 2025). "Herein, we find that tumor‐derived cyclic GMP‐AMP (cGAMP) activates a distinct STING pathway by inducing TBK1‐mediated phosphorylation of Eomes in γδ T cells during the early stage of tumor development is demonstrated." (PMID 39573933, 2025). "Together, these data indicate that preserving recruitment of TBK1 and IKKε kinases, along with their associated scaffolding proteins to the TNFR1 complex, is essential for tumor cells to resist T cell attack." (PMID 41315176, 2025). "Here, we revealed that the anti-tumor activity of DS is mediated through TBK1-dependent IFN-I signaling." (PMID 40625660, 2025). "In GC cells, TRIM28 significantly increases PD-L1 expression by activating the TBK1-mTOR pathway, suppressing T-cell activation, and promoting tumor progression." (PMID 40140647, 2025). "Xenograft experiments revealed that both amlexanox treatment and TBK1 knockdown effectively suppressed the tumor growth." (PMID 39744441, 2025). "We demonstrated, for the first time, that DS markedly inhibits tumor growth and sensitizes tumors to PD-1 blockade by activating TBK1-dependent IFN-I signaling through targeting LRP1." (PMID 40625660, 2025). "We found that TBK1 and IKKε are more highly expressed in tumor tissues than in normal tissues, consistent with other groups’ findings." (PMID 40738190, 2025). "TBK1 is a critical node in the innate immune pathway and mediates anti-tumor immunity by activating innate immune responses." (PMID 40822284, 2025). "We found that either knockdown or inhibition of TBK1 and IKKε reduced tumor sphere number and size in MIA PaCa-2 cells, potentially overlapping with effects on cell survival." (PMID 40738190, 2025). "The IKBKE/TBK1 inhibitor, Amlexanox, can repress cancer cell proliferation and invasion and has shown efficacy in different experimental tumor models." (PMID 40468448, 2025). "Together, these findings highlight the critical involvement of tumor-intrinsic, TBK1-dependent IFN-I signaling in mediating the anti-tumor effect of DS." (PMID 40625660, 2025).
tumor (continued). "Via Sec5, RalB has also been shown to activate tank-binding kinase 1 (TBK1) in an exocyst-independent manner to promote tumor cell survival." (PMID 40738882, 2025). "To determine if TBK1 and IKKε contribute to a cancer stemness phenotype, we performed tumor sphere assays using MIA PaCa-2 cells." (PMID 40738190, 2025). "Correspondingly, targeting TBK1 can enhance tumor cells responses to immune checkpoint blockade by decreasing the cytotoxicity threshold to effector cytokines including TNF." (PMID 39279883, 2024). "In contrast, acute activation of the cGAS-STING pathway often leads to anti-tumor immunity through TBK1-dependent activation of IRF3 and canonical NF-κB p65/p50 signaling, which mediate the transcription of type I IFN signaling." (PMID 38167338, 2024). "More importantly, we found the antimiRs(21+9+10b) treatment combined with the TBK1 inhibitor Amlexanox, which suppressed the formation and activity of oncogenic miRISCs, had the best anti‐tumor effect." (PMID 38351659, 2024). "The activation of the TBK1-IFN-I pathway has been attributed positive significance in anti-tumor responses and improved prognosis in many tumors." (PMID 39161768, 2024). "Recent studies have shown that targeting TBK1 can reduce the sensitivity of tumor cells to effector cytokines (such as TNF-α and IFN-γ), promote tumor cell apoptosis, and reverse tumor resistance to immunotherapy." (PMID 39161768, 2024). "STING regulates the activity of TBK1 by directly interacting with TBK1 in innate immunity, whereas the TBK1-mediated mTOR signaling pathway plays an important role in tumor progression." (PMID 39061024, 2024). "TBK1 activates several signaling pathways such as AKT-mTORand MYC that are responsible for tumor cell survival." (PMID 39289178, 2024). "In the context of cancer, TBK1’s multifaceted roles present a complex landscape wherein it can exhibit both oncogenic and tumor-suppressive properties." (PMID 38567349, 2024). "TBK1 acts as a pivotal node within the innate immune pathway, mediating anti-tumor immunity through the activation of innate immune responses." (PMID 39161768, 2024). "Innate immune sensing pathways activate the TBK1 kinase for phosphorylation of the actin dynamics regulator Zyxin to trap macrophages in the tumor." (PMID 39304793, 2024). "In particular, in the early stages of tumor development, the TBK1-IFN pathway creates a local inflammatory environment by stimulating immune cell activation and anti-tumor cytokine secretion." (PMID 39161768, 2024). "In KRAS mutant cells, K128 ubiquitination limits tumor growth by restricting RAL/ TBK1 signaling and negatively regulating the autocrine circuit induced by mutant KRAS." (PMID 38858602, 2024). "In cancer biology, evidence has highlighted the importance of the RALB/TBK1 pathway in cell autonomous survival by establishing a link between tumor formation and the innate immune response." (PMID 38519457, 2024). "Further research has revealed TBK1’s involvement in various aspects of tumorigenesis, including supporting tumor angiogenesis, mediating tumor-related autophagy, regulating cell cycle and mitosis, and inducing epithelial-mesenchymal transition (EMT)." (PMID 39161768, 2024). "The protein expression level of TBK1 also exhibited an upward trend in the tumor metastasis group, whereas the expression level of IRF3 demonstrated an opposing phenomenon." (PMID 38817870, 2024). "Tiopanib, a pan-PARP inhibitor, exploits the therapeutic vulnerability of PARPi-resistant tumor cells by activating the TBK1-IFN pathway." (PMID 39161768, 2024). "In this paper, we review the signaling pathways mediated by TBK1 in various tumor contexts and summarize the dual roles of TBK1 and the TBK1-IFN pathways in both promoting and inhibiting tumor progression." (PMID 39161768, 2024). "In our co-culture system, IFNB and IFNL1 mRNA expression were induced by tumor cell-targeted STINGa ADCs downstream of TBK1 signaling." (PMID 38992037, 2024).
tumor (continued). "To track the effect of PEG-MnMOF@PTX on STING pathway, we performed p-STING and p-TBK1 immunofluorescence staining on tumor tissues." (PMID 38715912, 2024). "Generally, these results suggest that the anti‐tumor function of ME49Δompdc/gra4 vaccination relies on TBK1." (PMID 39031880, 2024). "The anti-tumor and pro-tumor effects of TBK1-IFN are dynamic processes, and the appropriate time to target this pathway still needs to be further explored." (PMID 39161768, 2024). "While in some tumor cells, enriched cGAS/STING signaling kindles a tumor-promoting function by activating NF-κB, TBK1, and IRF3." (PMID 38474405, 2024). "It has been shown previously that CIN can activate chronic cGAS-STING signaling, which can promote tumor metastasis and survival through TBK1-independent activation of NC-NF-κB and IL-6-STAT3 signaling." (PMID 38167338, 2024). "Nevertheless, the use of TBK1 inhibitors requires careful consideration of tumor-specific signaling." (PMID 39161768, 2024). "In conclusion, TBK1 exhibits dual roles in tumor progression, with the expression of the IFN pathway potentially offering a crucial explanation for this contradiction." (PMID 39161768, 2024). "As a critical downstream pathway of TBK1, the dual role of IFNs in tumor progression has garnered attention, potentially offering key insights into the bifunctional nature of TBK1." (PMID 39161768, 2024). "Activation of these pathways in tumor cells induces the production of type I IFNs via the serine/threonine kinase TBK1 (TANK-binding kinase 1) and transcription factor IRF3 (IFN regulatory factor 3)." (PMID 38748789, 2024). "The results showed that compared with control group and DS-8201 treatment group, phosphorylation of TBK1 in EpCAM+ xenograft tumor cells was much higher in the ADU-S100 treatment group and combined treatment group." (PMID 38993569, 2024). "Apart from limitations in the potency and specificity of the drug itself, a primary reason is the lack of comprehensive understanding of tumor types and the inherent heterogeneity of tumor subtypes dependent on TBK1." (PMID 39161768, 2024). "Numerous literatures have shown that TBK1 can exhibit both tumor promoting and tumor inhibiting effects." (PMID 39161768, 2024). "Exploring interventions targeting the TBK1-IFN pathway in specific tumor contexts is imperative for enhancing therapeutic efficacy in cancer treatment." (PMID 39161768, 2024). "Niraparib activated anti-tumor CD8+T cells in the tumor microenvironment through the STING/TBK1/IRF3 pathway in EGFR-mutant NSCLC." (PMID 36865554, 2023). "A similar approach was used to determine the role of TANK-binding kinase 1 (TBK1) in tumor immune evasion." (PMID 38136325, 2023). "Inhibition of TBK1 resulted in impaired proliferation, migration, drug resistance, and tumor growth in CRC cells." (PMID 37671160, 2023). "Treatment with amlexanox, a selective inhibitor of TBK1, strongly suppressed tumor growth in these mice." (PMID 37357254, 2023). "The tumour growth curve and tumour weight results showed that tumours from TBK1-overexpressing cells grew significantly faster." (PMID 36928362, 2023). "The upregulation of TBK1 was significantly correlated with several aggressive clinicopathological characteristics, such as larger tumour diameter (P = 0.009), lymph node metastasis (P < 0.001), and advanced TNM stage (P = 0.001)." (PMID 36928362, 2023). "In line with this, TBK1 inhibition has been reported to increase immune reactivity to tumor organoids ex vivo." (PMID 36669486, 2023). "Increased p-TBK1 levels was also found in various murine tumor cells including B16-F10, MC-38 and CT26 and LLC in response to ATM inhibition." (PMID 36778120, 2023). "Administration of the PD-L1 or TBK1 inhibitor significantly alleviated the TRIM28-induced tumor progression." (PMID 37357254, 2023).
tumor (continued). "PARP7 inhibition causes tumor regression by enhancing antitumor immunity, which is dependent on the stimulator of interferon genes (STING) pathway, TANK-binding kinase 1 (TBK1) activity, and cytotoxic CD8+ T cells." (PMID 37509350, 2023). "To further explore the potential mechanism by which TBK1 promotes tumour progression, we performed RNA sequencing, and the results showed approximately 3101 differentially expressed genes (DEGs) after TBK1 knockdown." (PMID 36928362, 2023). "TNF- or IFN-γ-treated TBK1-null tumour cells promoted RIPK- and caspase-dependent cell death regulators." (PMID 37503572, 2023). "TBK1 activation in such tumor cells is primarily stimulated by TGFβ, which promotes the survival of tumor cells by activating AKT and YAP signaling pathways." (PMID 35395857, 2022). "The tumor growth from cells with TBK1 knockdown was substantially inhibited compared to that of the control group as judged by the tumor weight and tumor volume." (PMID 35637944, 2022). "The roles of TBK1 in tumor immunity in other immune cells, including T and B cells as well as monocytes/macrophages, have not been sufficiently evaluated." (PMID 35395857, 2022). "In the cytoplasm of cancer cells, TBK1 drives tumor development and progression by stimulating cell survival and proliferation pathways, including AKT-mTOR1, NF-κB, p62/autophagy, MYC, and JAK/STAT." (PMID 35395857, 2022). "NF-κB activator TANK-binding kinase 1 (TBK1) is a serine/threonine kinase with an ability to induce NF-κB signal and is highly expressed in a variety of tumor cells." (PMID 35659308, 2022). "In this case, dormant tumour cells upregulate their expression of several signalling receptors, such as Axl, TBK1, and N-cadherin, thereby allowing adhesive attraction of dormant tumour cells to osteoblasts." (PMID 36307871, 2022). "One of the main anti-tumor mechanisms of RSV seems to be related to the activation of TANK-binding kinase 1 (TBK1), whose insufficient activity would lead to autoimmune, neurodegenerative, or oncogenic diseases." (PMID 35409389, 2022). "TBK1 inhibitor BX795 inhibits tumor growth through inducing mitotic phase arrest and cell apoptosis in a pre-clinical model of oral squamous cell carcinoma (OSCC)." (PMID 35335873, 2022). "TBK1 is often highly expressed in tumors, and our TCGA data analysis shows that the expression of TBK1 in most tumor types was higher than in paracancerous controls." (PMID 36176304, 2022). "Studies on the relationship between cGAS/STING/TBK1 and distant metastasis of tumors have confirmed that the activation of cGAS/STING/TBK1 inhibits tumor metastasis by synthesizing IFN and recruiting NK cells and macrophages." (PMID 35844603, 2022). "The high expression of TBK1 was identified in HCC clinical specimens compared with paired non-tumor tissues." (PMID 35747750, 2022). "We then investigated the protein expression of p-STING, p-IRF3 and p-TBK1 in tumor tissues from different treatment groups." (PMID 35386310, 2022). "An example is TBK1, an atypical I-κB kinase family member that acts through the Ral guanine exchange factor (RalGEF) cascade to promote tumor signaling, including activation of AKT and NF-κB." (PMID 36523963, 2022). "The metastasis is also inhibited when TBK1-silenced tumor cells are incubated with platelets, suggesting that TBK1 is a key mediator in regulating platelet-induced EMT." (PMID 35659308, 2022). "The TBK1-dependent mTOR signaling activation in K-RAS/N-RAS-activated tumor cells suggests that TBK1-mTOR and MEK-ERK constitute parallel survival and proliferative signaling pathways in such tumor cells." (PMID 35395857, 2022). "TBK1 and IRF3 polymorphisms were investigated for their effects on tumor growth and vascularization and thus on response to bevacizumab therapy." (PMID 36432658, 2022). "TBK1 is often highly expressed in tumors, and TCGA data analysis shows that the ex-pression of TBK1 in most tumor types was higher than in paracancerous controls." (PMID 36176304, 2022).
tumor (continued). "In consequence, the interferon regulatory factors (IRF3/7) are activated through phosphorylation by TBK1 which promotes their nuclear entry for transcriptional activation of the inflammatory type I interferons and subsequent anti-tumor immunity." (PMID 35992877, 2022). "Researchers found that tumor-derived DNA was the ligand of STING pathway and was associated with phosphorylation of TBK1 and IRF3 and STING-dependent IFN-β." (PMID 35720348, 2022). "In the mouse model of cerulein-induced pancreatitis/K-RasG12D PDA, TBK1 in the tumor cells promotes neutrophil recruitment and T-cell infiltration by stimulating the production of cytokines, such as CCL5 and IL-6, and the upregulation of PD-L1." (PMID 35395857, 2022). "This ECM-independent clustering leads to the downstream activation of TBK1 and NF-κB, which regulates tumor initiation and anchorage-independent growth." (PMID 35763345, 2022). "The expression level of TBK1 was much higher in HCC cells compared with the non-tumor hepatic cell line L-02." (PMID 35747750, 2022). "The expression levels of TBK1 were much higher in HCC specimens compared with paired non-tumor tissues." (PMID 35747750, 2022). "In VHLnull ccRCC tumor cells, loss of VHL copy number results in hyperactivation of TBK1, which leads to increased autophagy, due to TBK1-mediated phosphorylation of p62/SQSTM1 on Ser366." (PMID 35395857, 2022). "Treatment with the TBK1 antagonist attenuated the HCC progression in vivo by enhancing the infiltration of CD8+ T cells in the tumor." (PMID 33679751, 2021). "TIMER and UALCAN were used to analyze the transcriptome-sequencing data from TCGA data set to evaluate the differences in TBK1 expression between tumor and normal samples." (PMID 33679751, 2021). "Due to the promoting effect of hepatic fibroinflammatory condition on the tumor immunosuppression, it is possible that the TBK1 antagonist attenuated the HCC immunosuppression by reducing the fibrosis and inflammatory environment of liver." (PMID 33679751, 2021). "The degrees of infiltration of CD4+ and CD8+ T cells in the tumors of immunocompetent mice were examined and indicated that the number of tumor-infiltrating CD8+ T cells was markedly increased after treatment with the TBK1 antagonist." (PMID 33679751, 2021). "In vivo experiments revealed that treatment with a TBK1 antagonist delayed HCC growth by increasing the number of tumor-infiltrating CD8+ T cells." (PMID 33679751, 2021). "In oncogenic KRas-transformed cells, TBK1 promotes cell proliferation and survival and the growth of tumor explants in vivo, with either mTORC1 or Akt suggested as downstream mediators of TBK1 action." (PMID 34245780, 2021). "An initial study linking TBK1 to cancer found that TBK1 supports oncogenic Ras transformation with coupling innate immune signaling to tumor cell survival." (PMID 33679751, 2021). "More importantly, TBK1 expression was positively correlated with a decreased number of tumor-infiltrating CD8+ T cells and increased immunosuppressive markers in patients with HCC." (PMID 33679751, 2021). "The association between TBK1 and HCC immune infiltrates, and its potential mechanism were investigated via analyses of the Tumor Immune Estimation Resource, tumor-immune system interactions database (TISIDB), CIBERSORT, STRING, and Metascape." (PMID 33679751, 2021). "Downstream interruption of KRAS-NF-κB signaling (i.e., inhibition of TBK1 with TBK1 shRNA) largely overcame integrin β3-mediated stemness (i.e., less tumor sphere formation in FGβ3 cells with TBK1 knockdown)." (PMID 32514015, 2020). "In this model, OPTN plays a central role in regulation of TBK1 functional activity to reverse tumor stemness and drug resistance in FGβ3 cells." (PMID 32514015, 2020). "Other functions of the TBK1-TBKBP1 axis relate to tumor growth and immunosuppression through induction of PD-L1." (PMID 33109261, 2020).